IL6 (interleukin 6)
Diseases named in the same sentence as IL6 in open-access papers (continued):
Sharing a sentence is not in itself a finding about the gene and the disease.
pneumonia (continued). "Similar to the results obtained with cell lines in vitro, IL-6 gene expression in lung tissue and IL-6 levels in BALF in a poly(I:C)-induced acute pneumonia were significantly enhanced by IFN-γ." (PMID 38030681, 2023). "Accordingly, in our work, we observed that key inflammatory markers (IL-6, TNF-α, IL-8, IL-1α, and IP-10) were elevated in serum from hospitalized women due to severe features, such as pneumonia." (PMID 36016660, 2022). "Acute pneumonia increased the expression of TNF-α, IFN-γ, IL-6, IL-2 and IL-17 genes, and decreased the expression of Foxp3, IL-10, and TGFβ1 genes in lung tissue homogenate of mice." (PMID 35782123, 2022). "Pre-existing T. spiralis infection decreased lung neutrophil recruitment, inflammatory mediator IL-1β and IL-6 expression and chemokine CXCL1 and CXCL2 release during P. aeruginosa- pneumonia." (PMID 35500031, 2022). "Correlation analysis showed that the IL-6, G-CSF, M-CSF, IFN-γ, and MCP-1 levels had positive correlations with the severity of pneumonia." (PMID 35382755, 2022). "Increased inflammatory cytokines, such as interleukin-6 (IL-6) and tumor necrosis factor alpha (TNF-α), are indeed observed in patients with severe pneumonia." (PMID 36135185, 2022). "Compared with the model group, isorhamnetin reduced the protein expressions of SYK, IL-6, MAPK14, MAPK8, TNF-α, AKT, p-Akt, PIK3CA, EGFR and IL-1β in lung tissues of pneumonia mice." (PMID 36506534, 2022). "Although IL-6 has a profibrotic effect, an experimental study suggested that inhibition of IL-6 in the early phase of lung injury induces fibrosis, while inhibition of IL-6 in later stages of pneumonia and at beginning of the fibrotic phase might ameliorate the lung fibrosis." (PMID 36010377, 2022). "Various studies have reported CAH in about 30% to 45% of children, with pneumonia due to SIADH, volume depletion, increased levels of IL-6, and renal impairment as possible mechanisms." (PMID 36556138, 2022). "Consistent with the previous findings, we found that levels of a variety of cytokines, such as IL-6, IL-1RN, and TNF-α, increased rapidly in the pneumonia cases, thereby accelerating the inflammatory response." (PMID 36119044, 2022). "The emerging or declining theme included “inflammation”, “cytokine storm”, “cytokines”, “ARDS”, “innate immunity”, “pneumonia”, “ACE2”, “biomarker”, “IL-6”, and “outcome”." (PMID 36405695, 2022). "Inflammatory cytokines induced by pneumonia‐related bacteria, such as Haemophilus influenzae and Streptococcus pneumoniae, are important in COPD exacerbation, and TNF‐α and IL‐6 levels are increased in sputum during COPD exacerbations." (PMID 35034433, 2022). "IL-6, G-CSF, M-CSF, IFN-γ, and MCP-1 levels had a positive correlation with the severity of pneumonia." (PMID 35382755, 2022). "The analysis results indicated IL-6 and TNF-α were effective biomarkers to differentiate between mild and severe symptoms in children diagnosed with HMPV pneumonia with an AUC of 0.678 (95% CI 0.526–0.829) and 0.658 (95% CI 0.506–0.809), respectively." (PMID 36496397, 2022). "On the basis of the blood biochemical index, children with severe pneumonia exhibited high levels of CRP, IL‐6, PCT, and D‐dimer." (PMID 35665444, 2022). "Similar to ex vivo studies detailed above, both IL-6 and CXCL2 mRNA expression was significantly enhanced in anti–LOX-1 mice following 24 hours of pneumonia." (PMID 36264633, 2022). "FMT has also shown decreased the levels of IL-6, LPS and IFN-γ in the serum of mice with acute pneumonia." (PMID 35782123, 2022). "We detected significant production of TNF-α and IL-6 in the BALF, which correlated with protection against pneumonia in the group immunized with rPspA-PlD1." (PMID 36477013, 2022). "Notably, the vascular endothelial marker IL-6 was significantly upregulated in the eight pneumonia cases, and IL-27, which negatively regulates inflammation, was also activated, suggesting that IL-6 may be an important marker of disease severity of psittacosis." (PMID 36119044, 2022).
pneumonia (continued). "Elevated concentrations of both pro- and anti-inflammatory plasma cytokines were observed in the pneumonia group, including G-CSF, HGF, IL-1b, IL-1RA, IL-2, IL-2Ra, IL-6, IL-10, IL-18, IP-10, monocyte chemoattractant protein-3 (MCP-3), and TNF-α." (PMID 36119044, 2022). "The IL-6 and TNF-α were used to differentiate between mild symptoms and severe symptoms in children diagnosed with HMPV pneumonia with an AUC of 0.678 (95% CI 0.526–0.829) and 0.658 (95% CI 0.506–0.809), respectively." (PMID 36496397, 2022). "Thus, we asked whether intervention with Stat3/IL-6 signaling inhibitors could blunt pneumonia." (PMID 35617354, 2022). "Second, curcumin protects from lethal pneumonia and ARDS via targeting NF-κB, inflammasomes, IL-6 trans-signal, and high-mobility group box 1 (HMGB1) pathways." (PMID 35496320, 2022). "Moreover, IL-6 and CXCL10 levels were significantly associated with the presence of pneumonia and the development of respiratory failure, thereby supporting the hypothesis that the elevation of these inflammatory biomarkers is possibly dominant in the pulmonary circulation." (PMID 35237279, 2022). "Recent clinical studies have shown a significant increase in the levels of IL6, TNF, and many other inflammatory factors, especially in patients with severe pneumonia." (PMID 34731090, 2021). "Very recently, Tsai and colleagues reported that salivary IL-6 and CRP levels are significantly higher in pediatric patients with pneumonia compared to healthy controls." (PMID 34708133, 2021). "Il-6 and CRP values upon admission, severe pneumonia, the highest oxygen flow value and infection with the variant alpha were associated with either death or transfer to the ICU in univariate analysis." (PMID 34441844, 2021). "The results showed significantly lower levels of IL-6, IFN-γ, and ICL in patients with chickenpox complicated by pneumonia as compared with uncomplicated forms of the disease." (PMID 34795992, 2021). "There were mildly increased levels of IL-6, IFN-γ, and ICL (less than double-normal values) in patients with chickenpox complicated by pneumonia." (PMID 34795992, 2021). "When compared to mild disease, patients that developed severe pneumonia had a significant increase in IL1-RA, IL-6, IP-10, MCP-1, MCP-3, M-CSF, and TNF-α." (PMID 34131192, 2021). "For example, potentially useful biomarkers for severe or refractory pneumonia include AST, ALT, LDH, CRP, ferritin, and various cytokines (IL-18, IL-6, or TNF-α)." (PMID 33810090, 2021). "Effect of RYNM on serum IL-10, NOS2, COX-1, IL-6, TNF-α and NF-κB levels in pneumonia model rats (mean ± S.D., n = 10)." (PMID 33678123, 2021). "In summary, a low serum level of 25-OH-VD was negatively associated with a lower risk of NIP and a significant correlation between 25-OH-VD level and pneumonia indicators (PCT and IL-6) was detected." (PMID 34643152, 2021). "Further, increases in IL-6, IL-8, IL-10, IL-15, TNF-α, and IFN-γ have been reported in severe pneumonia compared with mild pneumonia." (PMID 34692846, 2021). "After treatment with Bm (75, 150, and 300 μg/kg), TNF-α, IL-6, IL-1β, and PEG2 levels in Kp-induced pneumonia mice exhibited a downward trend in a dose-dependent manner." (PMID 34017253, 2021). "Procalcitonin (PCT), interleukin-6 (IL-6), C-reactive protein (CRP), sequential organ failure assessment (SOFA) and pneumonia severity index (PSI) scores, and mortality confirmed similar intriguing patterns." (PMID 32689999, 2020). "The four studies, respectively, showed that the IL-6 level of the XBJ group was lower compared with the control group with statistical significance indicating that XBJ combined with basic treatment could reduce the level of IL-6 in patients with severe pneumonia." (PMID 32908573, 2020). "In contrast, serum IL-6 levels and soluble CD40L (sCD40L) levels were higher in patients who developed severe pneumonia compared to those who developed DHF, although not significant." (PMID 33199778, 2020).
pneumonia (continued). "Specifically, three targets including IL-1β, IL-6, and TNF-α have been reported to be related to pneumonia, which were further validated in vivo." (PMID 32625244, 2020). "After adjusting for age, NIHSS score, pneumonia, WBC count, plasma IL-6, and TNFα release, the OR for poor functional outcome was 2.32 (95% CI 1.21–4.45, P = 0.01)." (PMID 32107751, 2020). "Neutrophil proportion, NLR, IL-6, ESR, CRP, and procalcitonin were generally higher in the pneumonia patients than in the pneumonia-free patients, in contrast to CD8+ and CD4+ T lymphocyte counts." (PMID 33239109, 2020). "With the progression of this disease to pneumonia, respiratory failure and death often occur in the first week, accompanied by an extreme rise in inflammatory factors such as IL2, IL6, IL10 and TNFα." (PMID 33226958, 2020). "Influenza virus FM1-infected pneumonia leads to an inflammatory storm, suggesting that many pro-inflammatory cytokines like TNF-α and IL-6 released into blood and lung tissue." (PMID 32625244, 2020). "The plasma concentrations of 11 inflammatory mediators with pro- and anti-inflammatory activity (IL-1, IL-4, IL-6, IL-8, IL-9, IL-15, eotaxin, bFGF, G-CSF, GM-CSF, and TNF-α) were higher in children with severe CAP than in children with mild pneumonia." (PMID 31183362, 2019). "Several studies have associated the excessive production of pro-inflammatory cytokines such as IL-1, IL-6 and TNF-α with the development of M. hyopneumoniae-induced pneumonia." (PMID 31703726, 2019). "The levels of the pro-inflammatory cytokines/chemokines including TNF-α, IL-1β, IL-6, MCP-1 and KC were significantly higher in the HNP+ pneumonia mice under HP ventilation than other groups." (PMID 30268129, 2018). "In the P. aeruginosa model of pneumonia with strain PAO1, IL-6 levels were significantly higher in hypoxia (P < 0.05) after 4 h of infection." (PMID 30082478, 2018). "At days 0 and 1 after admittance, a cutoff of 20,000 pg/mL IL-6 diagnosed a SIRS state (83% sensitivity; 75% specificity), and an IL-6 level above 300 pg/mL in SIRS patients was correlated with larger risks of complications, including pneumonia and death." (PMID 28487810, 2017). "Persistently high levels of IL-6, IL-8 and IL-10 in BAL fluid or serum have been found in severe pneumonia and NCAP, reflecting an ongoing inflammation." (PMID 25849726, 2015). "IL-6, MCP-1 and TNFα levels were all significantly decreased 24 hours after pneumonia in aged septic Mttp-IKO mice." (PMID 25010671, 2014). "A cytokine storm, or the upregulation of proinflammatory cytokines and chemokines, such as IL-6, IL-8, IFN-α, IP-10, MIG, MIP-1β, and MCP-1, is reported to have contributed to the lung injury and severe pneumonia in these H7N9-infected patients." (PMID 24676272, 2014). "The levels of IL-6 and CXCL10 were higher in children with PFAPA during febrile episodes than in children with pneumonia." (PMID 24134207, 2013). "The predictive power of IL-6, IL-10 and LBP for a severe course of pneumonia was lower than that of CRB-65." (PMID 22348735, 2012). "It was therefore unexpected that PAR-1 KO mice displayed higher concentrations of the proinflammatory cytokines TNF-α, IL-6 and IFN-γ in lung tissue during pneumonia." (PMID 23270594, 2012). "The levels of several pro- and anti-inflammatory cytokines (including IL-1β, IL-6, IL-10, IL-13, G-CSF and TNFα) were examined in BAL fluid 24 hours after the onset of pneumonia in both genotypes." (PMID 23145105, 2012). "ROC curves illustrate the accuracy of IL-6, LBP and IL-10 concentrations, and CRB-65 and CRB scores, in predicting a severe course of pneumonia." (PMID 22348735, 2012). "The optimal cut-off concentrations that showed the highest prognostic accuracy (highest sensitivity and specificity) for IL-6, LBP and IL-10 in predicting a severe course of pneumonia were calculated using data from the ROC analyses." (PMID 22348735, 2012).
pneumonia (continued). "There was sustained activation of the proinflammatory cytokines (IL-6, CXCL8/IL-8, CCL2/MCP-1, sTNFR-1) in severe pH1N1 pneumonia; the CXCL10/IP-10, CXCL9/MIG and IL-17A responses remained largely suppressed during the hospital course." (PMID 22022504, 2011). "In fact, these viruses markedly induced the expressions of pro-inflammatory cytokines and chemokines including IL6, IL1α, IL1β, TNFα, IFNγ and CCL5 in the lungs, resulting in severe pneumonia." (PMID 21826229, 2011). "Hyperactivation of the proinflammatory cytokines IL-6, CXCL8/IL-8, CCL2/MCP-1 and sTNFR-1 was found in pH1N1 pneumonia (2–15 times normal) and in complicated seasonal influenza, but not in milder pH1N1 infections." (PMID 22022504, 2011). "In our CF mice with PA508 pneumonia, E2 increased protein levels in BAL fluid of TNFα and IL-6 (upstream stimulators of IL-17 production) and also increased mRNA levels in lung tissue of IL-23 and the isoforms IL-17A and IL-17F." (PMID 21118573, 2010). "Authors found remarkably and consistently elevated serum levels of IL-6 and IL-8 in ARDS and/or severe pneumonia, differentiating these entities from cardiogenic pulmonary oedema." (PMID 15972108, 2005). "In HAP patients with subsequent septic shock, IL-1β, IL-6, IL-8 and IL-10 were superior predictive markers than TNF-α, E-selectin and conventional laboratory values and scores at the time of pneumonia diagnosis." (PMID 16280065, 2005). "These patients were statistically older (p < 0.001), had higher concentrations of CRP (p < 0.001), IL-6 (p < 0.001), and D-dimer (p < 0.001), and exhibited lower concentrations of hemoglobin (p = 0.006) compared to those without pneumonia." (PMID 40969806, 2025). "In addition, Machado showed that green propolis reduced the levels of IL-6 and TNF-α in pneumonia induced by LPS." (PMID 40430449, 2025). "In addition, IL-2, IL-4, IL-6, IL-10, TNF-α, and IFN-γ levels were elevated by varying amounts depending on the type of pneumonia." (PMID 41011430, 2025). "Some studies have reported that radiotherapy could prompt alveolar epithelial cells to release many cytokines, such as TNF-α, IL-6, IL-13, and TGF-β1, which in turn affect the development of pneumonia." (PMID 40821765, 2025). "Notably, there was a differential effect between IL6 and IL6R perturbation on hospitalization due to pneumonia." (PMID 40858837, 2025). "Additionally, the levels of the inflammatory cytokines IL-1β, IL-6, and TNF-α in bronchoalveolar lavage fluid (BALF) and plasma were significantly elevated in mice receiving FMT from patients with pneumonia." (PMID 40736248, 2025). "However, in the pneumonia subgroup, only T cells and their subsets were reduced, which was accompanied by elevated levels of the pro‐inflammatory factors CRP and IL‐6." (PMID 41146434, 2025). "At admission interleukin (IL)-6 (standardised mean difference: 1.41 (0.04-2.77), p = 0.04), cytokeratin fragment 21-1 (CYFRA21-1; 0.53 (0.19-0.86), p = 0.002) and leucocyte count (0.28 (0.05-0.50), p = 0.01) were higher in patients who developed pneumonia." (PMID 40520925, 2025). "IL-6 levels were notably higher in pneumonia patients compared to those without (SMD = 0.34 [95% CI: 0.17, 0.52], I2 = 29%)." (PMID 41585373, 2025). "Based on these findings, an ROC curve was constructed, demonstrating that the combined prediction of mechanical ventilation, CRP, PCT, IL-6, and IgA for ACD in children with severe pneumonia achieved an AUC of 0.882, significantly higher than the AUC of any single indicator (P < 0.05)." (PMID 41234411, 2025). "It only proposes the conclusion that IL-6 can be used in the assessment of immune response rather than in the differentiation of pathogens, thus highlighting IFN-γ’s critical role in lung immunity, which can be extrapolated to pneumonia contexts." (PMID 40572766, 2025). "In the comparison between vaccinated and unvaccinated patients with pneumonia, the levels of IL-6, CXCL10, LD, IFN-α, IFN-λ1, IFN-λ3, VEGF, and NLR were not different." (PMID 38694512, 2024).
pneumonia (continued). "After conducting LD analyses and eliminating confounding variables, the ultimate counts of IVs for CRP, SAA1, IL-6, TNF-α, WBC, GlycA, GI, dysentery, pneumonia, BP, BLA, PP, and UTI are 1,594, 1,959, 1,021, 1,911, 1,597, 1,871, 1,870, 1,965, 1,876, 1,875, 1,864, 1,877, and 1,888, respectively." (PMID 38585702, 2024). "IL-6 and IL-5 in the migraine group were statistically different from those in the pneumonia group without headache." (PMID 38356891, 2024). "On the other hand, serum levels of IL-6 were significantly higher in the vaccinated and unvaccinated patients with pneumonia than in those without pneumonia, respectively." (PMID 38694512, 2024). "In this study, we found that IL-6 was in high secretionin pneumonia group than that in the non-pneumonia group." (PMID 38233767, 2024). "Furthermore, Dicer, XPO5, SRSF3, and hnRNPA3 knockdown exaggerated the N protein-induced DNA damage, apoptosis, cytosolic DNA accumulation, upregulation of IFNβ, IL-6, and NKG2D ligands, and pneumonia." (PMID 39138195, 2024). "Of the 18 cytokines tested, only IL-6 and IL-1b secretion significantly increased on bilateral sides of HAE during the early stage of pneumonia-derived CVB4 infection, while multiple cytokine secretions significantly increased in HFMD-derived CVB4-infected HAE." (PMID 37725516, 2023). "The high concentration of IL-6, IL-17A, GM-CSF, and IFN-γ were found in the BAL liquid phase which may account for the volumetric inflammatory changes in severe patients with pneumonia." (PMID 37626620, 2023). "In influenza pneumonia (H1N1, H7N9), a high CRP value also correlated with disease severity, proving to be an independent predictor of mortality in the H7N9 infection, while leading to the cytokine storm characterized by elevated IL-6, MCP-1, and IP-10 levels." (PMID 37388734, 2023). "In an observational study, elderly patients with severe pneumonia exhibited lower levels of monocyte TLR2 and TLR4 expression, correlating with diminished serum concentrations of interleukin-1 (IL-1), interleukin-6 (IL-6), and TNF-α." (PMID 36829255, 2023). "Analysis of infected children during the 2009 influenza A (H1N1) virus pandemic revealed that levels of IFN-γ, IL-6, IL-8, IL-10, and other cytokines were higher in pneumonia patients than in non-pneumonia patients." (PMID 37249974, 2023). "In addition, changes in CRP, PCT, WBC, IL-6, Clostridium difficile toxin, and PSI pneumonia scores were assessed." (PMID 38050216, 2023). "Interestingly, high levels of NO, IL-6 and TNF-α expression in a mouse model of pneumonia were effectively lowered after treatment with polyphenol-rich extract from M. officinalis bark, which also provided long-term protection against reinfection." (PMID 36278162, 2022). "The serum levels of inflammatory cytokines, IL-6 and CXCL10, were significantly associated with pneumonia and hypoxemia, but not with the viral load in nasal-swab specimens." (PMID 35237279, 2022). "While LPS-induced acute pneumonia caused an increase in cytokine/chemokine mRNA expression, including that of IL-1β, -6, TNF-α, MCP-1, TauCl treatment attenuated IL-6, and TNF-alpha expression, but not IL-1β and MCP-1." (PMID 35448536, 2022). "Hence, IL-6 ≥ 7.20 pg/mL had a sensitivity of 85.0% and a specificity of 59.0% for severe HMPV pneumonia." (PMID 36496397, 2022). "Meanwhile, the results of molecular docking also exposed the active ingredients of YPFG could tack a part in modulating the progression of pneumonia via MMP9, CCL2, IL-1B, IL-6, CXCL8, and TNF." (PMID 36285159, 2022). "Moreover, in the current study sP-selectin correlated with IL-6, CRP and LDH which are clinically used as indicators of pneumonia severity, cytokine storm evolution and disease progression and are considered poor prognostic factors." (PMID 35061142, 2022).